GRIPAP1 (GRIP1 associated protein 1)
Description:
Regulates the endosomal recycling back to the neuronal plasma membrane, possibly by connecting early and late recycling endosomal domains and promoting segregation of recycling endosomes from early endosomal membranes. Involved in the localization of recycling endosomes to dendritic spines, thereby playing a role in the maintenance of dendritic spine morphology. Required for the activity-induced AMPA receptor recycling to dendrite membranes and for long-term potentiation and synaptic plasticity (By similarity). [GRASP-1 C-terminal chain]: Functions as a scaffold protein to facilitate MAP3K1/MEKK1-mediated activation of the JNK1 kinase by phosphorylation, possibly by bringing MAP3K1/MEKK1 and JNK1 in close proximity.
Synonyms: GRASP-1; KIAA1167; GRASP1; MPMGp800B12492Q3; DKFZp434P0630
Tractability: Antibody: UniProt places it where antibodies can reach, with high confidence. PROTAC: ubiquitination databases record sites on it; its protein half-life has been measured.
Gene: Protein-coding gene on chromosome X (48,973,719 to 49,002,265, reverse strand). Ensembl gene ENSG00000068400.
Subcellular location: Early endosome membrane; Recycling endosome membrane; Cell projection, axon; Cell projection, dendrite; Synapse
Subcellular location (Human Protein Atlas): Cytosol; Vesicles
Gene Ontology:
Molecular function: identical protein binding; protein binding; guanyl-nucleotide exchange factor activity; ionotropic glutamate receptor binding
Biological process: regulation of neurotransmitter receptor transport, endosome to postsynaptic membrane; regulation of recycling endosome localization within postsynapse; negative regulation of protein localization; negative regulation of receptor clustering
Cellular component: blood microparticle; extrinsic component of postsynaptic early endosome membrane; glutamatergic synapse; axon; dendrite; early endosome membrane; neuronal cell body; presynaptic membrane; recycling endosome membrane; synapse
Homologues: Orthologues: macaque GRIPAP1 (98% identical), chimpanzee GRIPAP1 (96% identical), dog GRIPAP1 (94% identical), mouse Gripap1 (93% identical), rat Gripap1 (93% identical), rabbit GRIPAP1 (91% identical), pig GRIPAP1 (89% identical), guinea pig GRIPAP1 (79% identical), zebrafish gripap1 (65% identical), tropical clawed frog gripap1 (62% identical).
Diseases named in the same sentence as GRIPAP1 in open-access papers:
GRIPAP1 is named in the same sentence as 13 diseases in open-access papers, as found by Europe PMC text mining. Sharing a sentence is not in itself a finding about the gene and the disease. The quoted sentences say what the papers report.
autism (2 papers, 2015 to 2021). Persistent deficits in social interaction and communication and interaction as well as a markedly restricted repertoire of activity and interest as well as repetitive patterns of behavior. "GRIPAP1 is located at Xp11, a region subject to duplication that has been previously associated with Autism with severe Intellectual Disability." (PMID 25679214, 2015). "Four genes cg23920016 (NOS1AP), cg24274662 (MOSPD1), cg26017408 (AFAP1L2) and cg16930349 (GRIPAP1) identified based on predictive ability for autism using AI analysis." (PMID 34260616, 2021).
breast carcinoma (1 paper, 2021). "Upregulation of tRNAGluUUC and tRNAArgCCG promotes breast cancer metastasis, with tRNAGluUUC promoting metastatic progression by directly enhancing exosome component exosome component 2 (EXOSC2) and glutamate receptor interacting protein 1 (GRIP1) associated protein 1 (GRIPAP1) protein expression." (PMID 36046433, 2021).
cognitive decline (1 paper, 2024). "A recent study investigating X chromosome gene expression found that several genes (including GRIA3, GPRASP2, and GRIPAP1) were associated with slower cognitive decline in women but not men." (PMID 39231932, 2024).
cutaneous melanoma (1 paper, 2023). A primary melanoma arising from atypical melanocytes in the skin. "However, four genes, i.e., HPDL, GRIPAP1, GBP2, and TRIM34, have been reported to exhibit prognostic significance with respect to melanoma for the first time, while HAPLN3, CCL8, FCGR2A, and IFITM1 have been reported to relate with the initiation and immune microenvironment of cutaneous melanoma." (PMID 36818162, 2023).
tumor (3 papers, 2018 to 2024). "Antigens like Flotillin1/2, GRIPAP1, or CLIP1 are also expressed in non-neural tissues without a tumor association." (PMID 30038610, 2018).
cancer (2 papers, 2021 to 2023). A tumor composed of atypical neoplastic, often pleomorphic cells that invade other tissues. "Then, LASSO and stepwise regression analyses were performed to construct PPRS by incorporating 8 prognostic genes, among which, 7 (except GRIPAP1) were associated with cancer." (PMID 36818162, 2023). "EXOSC2 and GRIPAP1 are downstream target proteins of tRNAGluUUC to promote the progression of cancer invasion and metastasis." (PMID 34048096, 2021).
GRIPAP1 also shares sentences with these, for which no sentence is quoted: cognitive disorder (1 paper); immune deficiency (1); infection (1); insulinoma (1); melanoma (1); perivascular epithelioid cell neoplasms (1); translocation renal cell carcinoma (1).